CEBPB (CCAAT enhancer binding protein beta)
Description:
Important transcription factor regulating the expression of genes involved in immune and inflammatory responses. Also plays a significant role in adipogenesis, as well as in the gluconeogenic pathway, liver regeneration, and hematopoiesis. The consensus recognition site is 5'-T[TG]NNGNAA[TG]-3'. Its functional capacity is governed by protein interactions and post-translational protein modifications. During early embryogenesis, plays essential and redundant roles with CEBPA. Has a promitotic effect on many cell types such as hepatocytes and adipocytes but has an antiproliferative effect on T-cells by repressing MYC expression, facilitating differentiation along the T-helper 2 lineage. Binds to regulatory regions of several acute-phase and cytokines genes and plays a role in the regulation of acute-phase reaction and inflammation. Also plays a role in intracellular bacteria killing (By similarity). During adipogenesis, is rapidly expressed and, after activation by phosphorylation, induces CEBPA and PPARG, which turn on the series of adipocyte genes that give rise to the adipocyte phenotype. The delayed transactivation of the CEBPA and PPARG genes by CEBPB appears necessary to allow mitotic clonal expansion and thereby progression of terminal differentiation. Essential for female reproduction because of a critical role in ovarian follicle development (By similarity). Restricts osteoclastogenesis: together with NFE2L1; represses expression of DSPP during odontoblast differentiation (By similarity). [Isoform 2]: Essential for gene expression induction in activated macrophages. Plays a major role in immune responses such as CD4(+) T-cell response, granuloma formation and endotoxin shock. Not essential for intracellular bacteria killing. [Isoform 3]: Acts as a dominant negative through heterodimerization with isoform 2. Promotes osteoblast differentiation and osteoclastogenesis (By similarity).
Synonyms: LAP; TCF5; CRP2; NFIL6; IL6DBP; C/EBP-beta; NF-IL6
Tractability: PROTAC: UniProt records ubiquitination sites on it; ubiquitination databases record sites on it; its protein half-life has been measured.
Gene: Protein-coding gene on chromosome 20 (50,190,734 to 50,192,690, forward strand). Ensembl gene ENSG00000172216.
Subcellular location: Nucleus; Cytoplasm
Subcellular location (Human Protein Atlas): Nucleoplasm
Pathways (Reactome):
Cellular responses to stimuli: ATF4 activates genes in response to endoplasmic reticulum stress; Response of EIF2AK1 (HRI) to heme deficiency; Response of EIF2AK4 (GCN2) to amino acid deficiency; Senescence-Associated Secretory Phenotype (SASP)
Developmental Biology: Transcriptional regulation of granulopoiesis; Transcriptional regulation of white adipocyte differentiation
Disease: Nuclear events stimulated by ALK signaling in cancer
Gene expression (Transcription): Transcriptional Regulation by VENTX
Gene Ontology:
Molecular function: protein binding; RNA polymerase II transcription regulatory region sequence-specific DNA binding; sequence-specific double-stranded DNA binding; transcription cis-regulatory region binding; DNA binding; DNA-binding transcription factor activity; DNA-binding transcription factor activity, RNA polymerase II-specific; DNA-binding transcription repressor activity, RNA polymerase II-specific; protein homodimerization activity; RNA polymerase II cis-regulatory region sequence-specific DNA binding; chromatin binding; chromatin DNA binding; DNA-binding transcription activator activity, RNA polymerase II-specific; DNA-binding transcription factor binding; histone acetyltransferase binding; histone deacetylase binding; identical protein binding; kinase binding; nuclear glucocorticoid receptor binding; protein heterodimerization activity; RNA polymerase II core promoter sequence-specific DNA binding; RNA polymerase II-specific DNA-binding transcription factor binding; sequence-specific DNA binding; ubiquitin-like protein ligase binding
Biological process: positive regulation of biomineral tissue development; positive regulation of DNA-templated transcription; positive regulation of sodium-dependent phosphate transport; positive regulation of transcription by RNA polymerase II; regulation of DNA-templated transcription; regulation of transcription by RNA polymerase II; response to endoplasmic reticulum stress; acute-phase response; defense response to bacterium; hepatocyte proliferation; immune response; inflammatory response; integrated stress response signaling; intrinsic apoptotic signaling pathway in response to endoplasmic reticulum stress; liver regeneration; myeloid cell development; negative regulation of T cell proliferation; negative regulation of transcription by RNA polymerase II; ovarian follicle development; positive regulation of cold-induced thermogenesis; positive regulation of fat cell differentiation; positive regulation of interleukin-4 production; regulation of cell differentiation; regulation of odontoblast differentiation; regulation of osteoclast differentiation; and 10 more
Cellular component: C/EBP complex; CHOP-C/EBP complex; cytoplasm; nucleoplasm; nucleus; RNA polymerase II transcription regulator complex; chromatin; condensed chromosome, centromeric region; nuclear matrix
Genetic constraint (gnomAD): Loss-of-function variants: 2 observed, 3.26 expected, observed/expected ratio (o/e) 0.61, 90% interval 0.25 to 1.68. That is too few expected variants to judge how well the gene tolerates losing a copy. Missense variants: 498 observed, 346.37 expected, observed/expected ratio (o/e) 1.44, 90% interval 1.34 to 1.55. Synonymous variants: 295 observed, 192.01 expected, observed/expected ratio (o/e) 1.54, 90% interval 1.4 to 1.69.
Homologues: Orthologues: chimpanzee CEBPB (100% identical), macaque CEBPB (99% identical), dog CEBPB (99% identical), pig CEBPB (98% identical), rabbit CEBPB (85% identical), mouse Cebpb (71% identical), rat Cebpb (71% identical), guinea pig CEBPB (60% identical), tropical clawed frog cebpb (51% identical), zebrafish cebpb (36% identical), Caenorhabditis elegans zip-4 (19% identical), Drosophila melanogaster slbo (17% identical), and 1 more. Paralogues in human: CEBPA (31% identical), CEBPD (27% identical), CEBPE (26% identical), CEBPG (13% identical).
Diseases named in the same sentence as CEBPB in open-access papers:
CEBPB is named in the same sentence as 310 diseases in open-access papers, as found by Europe PMC text mining. Sharing a sentence is not in itself a finding about the gene and the disease. The quoted sentences say what the papers report.
breast cancer (107 papers, 2006 to 2026). A primary or metastatic malignant neoplasm involving the breast. "Elevation in expression of CEBPB has been linked with progression of glioblastoma, lymphoma, and breast cancer." (PMID 34282050, 2021). "In 4w-11 tumors, CEBPA, which is associated with breast cancer progression was down-regulated and CEBPB, a gene found to be up-regulated in breast cancer as well as mouse mammary tumors, is up-regulated." (PMID 17147824, 2006). "In the realm of immunity, inhibiting glycolysis in breast cancer patients via the CEBPB pathway impedes G‐CSF and GM‐CSF production, reducing myeloid‐derived suppressor cells (MDSCs) and enhancing anti‐tumour immunity." (PMID 38982317, 2024). "Consistent with our findings, we reveal CEBPB's impact on breast cancer chemoresistance through the SPP1 signalling pathway." (PMID 38982317, 2024). "Recent studies had revealed that the expression of CEBPB was high in ovarian cancer, breast cancer, and colorectal cancer." (PMID 36120545, 2022). "Further, L01 treatment increased the amount of CHOP coimmunoprecipitated with CEBPB in Nic treated breast cancer cells." (PMID 31019204, 2019). "The oncogenic subunit of mucin 1 (MUC1-C), which is aberrantly overexpressed in many human breast cancers, activates ERK signaling and the CCAAT/enhancer-binding protein β (CEBPβ) transcription factor in breast cancer cells." (PMID 30733805, 2019). "CHOP was shown to be O-GlcNAcylated during Nic stress, and the increase inf O-GlcNAcylation significantly decreased the binding of CHOP to CEBPB, subsequently increasing the DNA-binding activity of CEBPB to the GFAT promoter in breast cancer cells." (PMID 31019204, 2019). "Classification of primary breast cancer RNASeq data based on high/low CEBPB/REST/CTCF revealed that, KRT5, KRT14 and KRT17 mRNAs were significantly upregulated in CEBPBhigh and CTCFlow tumors." (PMID 30335837, 2018). "First, CEBPB is significantly upregulated in TNBCs compared to other breast cancer molecular subtypes (p<0.0001)." (PMID 30335837, 2018). "The heatmaps indicated that REST expression is inversely correlated to CEBPB expression in primary breast cancers." (PMID 30335837, 2018). "The promoter of BC041455 is endogenously bound in multiple human cell types by CEBPβ, a transcription factor that is a known inducer of cell death in breast cancer." (PMID 28003470, 2016). "We found that loss of CCAAT-enhancer binding protein beta (C/EBPβ), a differentiation factor for the mammary epithelium, was associated with signs of EMT in triple-negative human breast cancer, and in invasive areas of mammary tumors in MMTV-PyMT mice." (PMID 23955085, 2013). "Notably, CEBPB enhances the stem cell characteristics of cancer cells by upregulating genes related to epithelial-mesenchymal transition, thereby accelerating breast cancer progression." (PMID 40536817, 2025). "Finally, KM Plotter analysis of the hub genes showed that the high expression of ADM, ENO1, PLOD1, and CEBPB was significantly correlated with a shorter OS and poor prognosis in patients with breast cancer." (PMID 37391802, 2023). "CEBPB was found to be involved in aerobic glycolysis and promote growth of breast cancer." (PMID 37056778, 2023). "Elevated expression of CEBPB has been identified in breast cancer, colorectal cancer, and glioma." (PMID 37985807, 2023). "PAK4-mediated CEBPB activation upregulates CLDN4 expression to promote cell migration and invasion in breast cancer, thus, PAK4/CEBPB/CLDN4 may be a potential therapeutic target in breast cancer treatment." (PMID 34490085, 2021). "One study based on breast cancer found that CEBPB was a novel transcriptional regulator of CLDN4." (PMID 32677948, 2020). "In MCF-7 breast cancer (BC) cell lines, transcription factors like CEBPb have been shown to induce P-gp expression." (PMID 35743927, 2022).
breast cancer (continued). "This increases Stat5a-mediated transcription and elevates the protein expression of breast cancer proliferative genes, such as CISH, CEBPb (CCAAT/enhancer binding protein β), and cyclin D1, which promote the proliferation of breast cancer." (PMID 40092489, 2025). "A number of these, such as CEBPB, ZNF117 and ZNF92, have been previously proposed as breast cancer markers and ZNF273 and ZNF727 have been reported as breast cancer hub genes." (PMID 38561804, 2024). "In another study on breast cancer, upregulated CEBPB/AEP (asparaginyl endopeptidase) can mediate oxidative stress and promote lung metastasis of breast cancer." (PMID 38710698, 2024). "The expression of Claudin-4 (CLDN4) is positively correlated with PAK4 in breast cancer and PAK4 induces CCAAT/enhancer binding protein β (CEBPB) activation, resulting in upregulation of CLDN4." (PMID 36105226, 2022). "A large number of factors were discovered that bind within 10,000 bases of the ACBD3 transcription start site across all tissues, and some of these stand out as having roles in breast cancers, including NOTCH1-NICD, CDK9, CTCF, and CEBPB." (PMID 36012147, 2022). "CCAAT enhancer binding protein beta (C/EBP beta) is involved in various cellular processes and has recently been reported as an essential mediator of breast cancer development." (PMID 33952249, 2021). "Collectively, our results reveal that CEBPB activates endogenous GFAT expression and increases cellular O-GlcNAcylation in Nic-treated breast cancer cells." (PMID 31019204, 2019). "Nic mediates production of UDP-GlcNAc and hyper-O-GlcNAcylation through CEBPB-dependent activation of GFAT and HBP flux, which further promotes EMT and motility in breast cancer." (PMID 31019204, 2019). "In conclusion, our results have revealed a new regulatory mechanism involving CEBPB/GFAT-induced hyper-O-GlcNAcylation that plays a key role in EMT and smoking-mediated breast cancer progression." (PMID 31019204, 2019). "We next sorted the RNASeq data of primary breast cancer patients based on RESTlow and RESThigh groups with 300 patients for each group and examined the expression patterns of TBP, CEBPB, REST, CTCF, RAD21 and SMC3 in addition to unsorted patient dataset." (PMID 30335837, 2018). "Additionally, CEBPB regulates breast cancer cell migration and invasion through diverse pathways, including THBS2 suppression, the PAK4–CEBPB–CLDN4 axis and the cAMP/AMPK/CEBPB axis." (PMID 38982317, 2024). "Knockdown of phosphoglycerate mutase 1 (PGAM1) could reconstruct the expression of ASS1 in breast cancer (BC) cells, resulting in a decrease in tumor growth and exerting antitumor effects via cAMP/AMPK/CEBPB axis." (PMID 35674458, 2022). "Altogether, the studies demonstrate that aberrant translation of the CEBPB-mRNA into its different protein isoforms plays a crucial role in breast cancer development, although we do not fully understand the underlying complexity." (PMID 35042889, 2022). "This locus contains 24 protein-coding genes, among which at least 10 (e.g. NCOA3, SNAI1/Snail1, CEBPB and PTPN1) are involved in mammary gland development, ERα-related regulation, or breast cancer, suggesting an importance of this locus for mammary gland morphogenesis." (PMID 31642473, 2019). "Furthermore, O-GlcNAcylation of the transcriptional repressor C/EBP homologous protein (CHOP) suppressed its binding to CEBPB and generated positive feedback that enhanced GFAT expression and EMT activation in breast cancer cells." (PMID 31019204, 2019). "Therefore, the O-GlcNAc modification of CHOP is important for its transcriptional inhibition of CEBPB as well as for Nic-induced and GFAT-dependent EMT activation in breast cancer cells." (PMID 31019204, 2019). "Previous studies have shown that the expression of CEBPB is not altered much in breast cancer vs." (PMID 39268460, 2024).
breast cancer (continued). "We have uncovered a previously unknown signaling pathway implicating p21-activated kinase 4 (PAK4) in the control of senescence in breast cancer, via the nuclear factor kappa-light-chain-enhancer of activated B cells (NF-κB) subunit RELB and the CCAAT-enhancer-binding protein beta (C/EBPβ)." (PMID 32158912, 2020). "By contrast, PugNAc reduced the interaction with CHOP relative to CEBPB in breast cancer cells without Nic stimulation, indicating that O-GlcNAc modification of CHOP could represent an obstacle to its interaction with CEBPB." (PMID 31019204, 2019). "To study whether m6A modification of the CEBPB mRNA contributes to its translational regulation, we applied FTO knockdown (shFTO) in triple‐negative MDA‐MB‐231 and luminal A‐type MCF‐7 breast cancer cell lines, and mouse embryonic fibroblasts (MEFs)." (PMID 40022434, 2025).
Obesity (54 papers, 2010 to 2026). Accumulation of substantial excess body fat. "Their variants affect the obesity risk by modulating the binding affinity of obesity-related transcription factors, such as STAT3, CEBPB, TCF7L2, FTO, and GATA2, and changing the phosphorylation of proteins, such as BDNF with the rs6265 risk allele." (PMID 34836030, 2021). "CCAAT/enhancer binding protein-β (CEBPB) is a major regulator of obesity and also regulates inflammation in the context of obesity." (PMID 32704163, 2020). "KLF15, CEBPA, and CEBPB are crucial for the early stages of adipocyte differentiation, and their downregulation in ASCs may reflect a shift away from adipogenic potential as obesity progresses." (PMID 40518865, 2025). "Therefore, we hypothesized that the obesity driver CEBPB might shed light on the biology of obesity, and neurodegenerative phenotypes at the cellular level and C19MC might have a role in it." (PMID 41282072, 2025). "In addition, the repressed expression of CEBPB has been found in obesity and T2D in adipose tissue." (PMID 33381155, 2020). "They reported that adipogenic and insulin signaling genes (CEBPB, PPARG, ADIPOQ, IRS-1, IRS-2, GLUT4, among others) were downregulated in obesity." (PMID 36432612, 2022). "The clustering revealed that HDAC2, CEBPB, and EP300 (Cluster 7) were transcriptional regulators for genes dysregulated in obesity and normalized by RSV and CR in both DIO zebrafish and obese human." (PMID 26441656, 2015). "Therefore, the CEBPB, and C19MC regulated Mon-gene-signature genetically links obesity, neurodegeneration, and cancer phenotypes in the context of defective autophagy at the cellular level." (PMID 41282072, 2025). "Therefore, a CEBPB and C19MC-driven Mon-gene-signature regulates the podosomal belt, lipid droplet, HBV, and DEPTOR mRNA dynamics to genetically link obesity, and neurodegeneration at the cellular level." (PMID 41282072, 2025). "Indeed, the binding regions of EP300, CEBPB, and HDAC2 in the promoters of transferrin (TF), insulin-like growth factor binding protein 1 (IGFBP1) and NQO1, whose expression was increased in obesity and was normalized by CR or RSV, overlap." (PMID 26441656, 2015).